ESPL1 (extra spindle pole bodies like 1, separase)
Diseases named in the same sentence as ESPL1 in open-access papers (continued):
Sharing a sentence is not in itself a finding about the gene and the disease.
cancer (continued). "First, we analyzed the expression of ESPL1 across all cancers included in the TCGA, including BC, using publicly available web-based tools such as TIMER 2.0, UALCAN, FIREHOSE, and OncoMX." (PMID 41268575, 2025). "Dysregulation of Extra Spindle Pole Bodies Like 1 (ESPL1), a mitotic regulator essential for chromosomal segregation, is frequently upregulated in cancers." (PMID 41268575, 2025). "Considering the importance of miRNAs in tumour development and early diagnosis of cancer, we utilised four online tools to predict the upstream miRNAs regulating ESPL1." (PMID 38813236, 2024). "The random-effects model results showed that the ESPL1 mRNA expression in the cancer groups was higher overall than that in the control groups (SMD = 0.75; 95 % CI = 0.09, 1.40)." (PMID 38813236, 2024). "Among the 11 datasets included, seven were found to have statistically significantly higher ESPL1 mRNA expression in the cancer group (p < 0.05)." (PMID 38813236, 2024). "We first examined the dependence of 1095 tumour cell lines on ESPL1; the results suggested that ESPL1 was indispensable for the growth and reproduction of all the examined cancer cell lines, including BC cell lines (chronons score < −1)." (PMID 38813236, 2024). "The high expression of ESPL1 was found to play a cancer-promoting role and affect the drug sensitivity of BC patients." (PMID 38813236, 2024). "We first compared the difference in expression of ESPL1 between cancer and normal tissues and found that ESPL1 was commonly highly expressed in cancers." (PMID 37006282, 2023). "Next, we evaluated the level of ESPL1 expression in multiple cancer types at different pathological stages." (PMID 37006282, 2023). "Previous studies have confirmed that ESPL1 is an oncogene that is overexpressed in many human cancers of breast, bone, brain, and prostate." (PMID 37006282, 2023). "Our findings indicate that higher levels of SEC31A1 are positively associated with increased IC50 values of cancer therapy drugs, whereas the expression of TOPBP1, ESPL1, and CPSF3 displayed an opposite correlation." (PMID 37417208, 2023). "We found that cell proliferation in both cancer cell lines was significantly inhibited following interference with ESPL1 expression." (PMID 37006282, 2023). "It was found that the expression of ESPL1 was negatively correlated with these scores in most cancers." (PMID 37006282, 2023). "First, we investigate the relationship between ESPL1 expression and the prognosis for survival of common cancers." (PMID 37006282, 2023). "To validate the oncogene nature of ESPL1, we have performed a knockdown of the target gene in various cancer cell lines to verify the effect of ESPL1 on proliferation and migration." (PMID 37006282, 2023). "Combining multi-omics data with bioinformatics, we have thoroughly described the function of ESPL1 in cancer." (PMID 37006282, 2023). "Comparing cancer tissues to normal tissues revealed that ESPL1 was highly elevated in a number of malignancies." (PMID 37006282, 2023). "Consistently, ESPL1 expression was significantly elevated in cancer samples across all eight datasets." (PMID 37006282, 2023). "The five prognostic DCLs tended to condense around the well-known cancer gene ESPL1, and the transcriptional synchrony between ESPL1 and PTTG1 (another well-known cancer gene) tended to be elevated in patients of adverse prognosis." (PMID 34856998, 2021). "Research has confirmed that extra spindle pole bodies-like 1 (ESPL1), an etiological factor, promotes the malignant progression of cancers." (PMID 34512713, 2021). "In particular, five prognostic gene links for kidney renal papillary cell carcinoma tended to condense around cancer gene ESPL1, and the transcriptional synchrony between ESPL1 and PTTG1 tended to be elevated in patients of adverse prognosis." (PMID 34856998, 2021).
cancer (continued). "Literature retrieval showed that the expression of CDCA5 was associated with tumorigenesis and tissue invasion in a variety of cancers, while the results on the roles of ESPL1, CDC45, and ESPL1 in cancers were conflicting." (PMID 34143800, 2021). "Gene set enrichment analysis (GSEA) indirectly revealed that ESPL1 regulates the activation of cancer-related pathways, such as the cell cycle and base excision repair pathways." (PMID 34512713, 2021). "ESPL1, also known as extra spindle poles-like 1 protein or separin, plays a central role in chromosome segregation by cleaving the cohesin complex at the onset of anaphase, and altered ESPL1 activity is correlated with aneuploidy and cancer." (PMID 34143800, 2021). "Last, TTK, CDC25A, and ESPL1 showed higher expression in the late cancer stage and higher tumour grade." (PMID 33282948, 2020). "The genes (CDC45, ESPL1 and RAD54L) in our prognostic model have been previously reported to be associated with various cancers." (PMID 32425694, 2020). "Further work is required to resolve the conflicting roles of ESPL1 in cancer and determine its function in BC." (PMID 31828101, 2019). "In human cancer, ESPL1/separase is frequently overexpressed and/or overactive resulting in deregulated proteolytic activity associated with supernumerary centrosomes, chromosomal missegregation and aneuploidy." (PMID 29370237, 2018). "In this regard, dysregulated cell cycle is one of the hallmarks of cancer; herein, extra spindle pole bodies-like 1 (ESPL1) is a cysteine endopeptidase or separase that helps sister chromatids stick together before and separate at the right time during anaphase." (PMID 41268575, 2025). "ESPL1 expression was the highest in the S and G2 phases of cancer cells, suggesting that ESPL1 might promote mitosis and tumour proliferation by regulating these phases of the cancer cell cycle." (PMID 38813236, 2024). "In addition, ESPL1 played a central protective role in cancer cells by converting the normally protective proteins MCL1 and Bcl-XL into pro-apoptotic agents." (PMID 38402402, 2024). "In addition to mTOR, Separase (ESPL1) is another target of LAT-3 which is involved in the cancer cell cycle, and suppression of LAT-3 leads to cell cycle arrest and decreases the number of cells in the S and G2/M phases." (PMID 38705513, 2024). "Considering that numerous genes highly expressed in cancer tissues affect patient prognosis, we speculated that ESPL1 also impacts patient survival." (PMID 37006282, 2023). "Therefore, we analyzed the correlation between ESPL1 expression in various cancers and the immune cells/scores using the XCELL algorithm." (PMID 37006282, 2023). "Through the use of public data mining, we were able to confirm that ESPL1 is an oncogene, that it can serve as a prognostic marker for several cancers, that it can be used to direct cancer medication therapy in patient derived organoids, and that ESPL1 knockdown can limit cell growth in vitro." (PMID 37006282, 2023). "Additionally, ESPL1 expression is associated with TMB, MSI, MATH, and HRD in several cancer types, suggesting a connection with tumor heterogeneity." (PMID 37006282, 2023). "Enrichment analysis showed that ESPL1 is involved in mediating multiple cancer-related pathways." (PMID 37006282, 2023). "We hypothesized that the expression level of ESPL1 may vary in different patients with the same cancer type." (PMID 37006282, 2023). "Taken together, our study provides evidence that ESPL1 may implicate tumorigenesis and disease progression across multiple cancer types, highlighting its potential utility as both a prognostic indicator and therapeutic target." (PMID 37006282, 2023). "Moreover, we identified ESPL1 specific genes and signaling pathways that regulate cancer progression and finally performed a drug correlation analysis." (PMID 37006282, 2023). "ESPL1 is highly expressed in these cancers, and the prognosis is worse for high expression." (PMID 37006282, 2023).
cancer (continued). "We utilized the UALCAN database to explore the DNA methylation level of ESPL1 in human cancer." (PMID 35814478, 2022). "In this study, we first analyzed ESPL1 expression in diverse cancers." (PMID 35814478, 2022). "At present, the results on the roles of ESPL1 in cancers are conflicting." (PMID 34143800, 2021). "In addition, TTK, CDC25A, and ESPL1 showed higher expression in cancers with late stage and higher tumour grade, compared with early stage and lower tumour grade (P < 0.05)." (PMID 33282948, 2020). "Lastly, TTK, CDC25A, and ESPL1 showed higher expression in cancers with late stage and higher tumour grade, which indicates that they may be potential targets for improving EC patient prognosis." (PMID 33282948, 2020). "Taken together, these results suggested that a protein network including AURKA, RAD54L, CDC45, and ESPL1 proteins, key molecules of pathways deregulated in cancer, could represent a common regulatory signature to all BC subtypes." (PMID 32932728, 2020). "TTK, CDC25A, and ESPL1 showed higher expression in cancers with late stage and higher tumour grade." (PMID 33282948, 2020). "However, high ESPL1 expression was associated with better OS prognosis in THYM patients, implying that ESPL1 may be protective in this cancer." (PMID 37006282, 2023). "We postulated that ESPL1 could potentially serve as a marker for predicting cancer development." (PMID 37006282, 2023). "In addition, we examined the impact of ESPL1 on the proliferation of numerous cancer cell lines." (PMID 37006282, 2023). "Furthermore, we explore the prognostic significance of ESPL1 in various human cancer types." (PMID 35814478, 2022). "Therefore, ESPL1 could serve as a marker for cancer therapy." (PMID 37006282, 2023). "Given that CNV and DNA methylation play crucial roles in modulating gene expression and are involved in cancer progression, we used the GSCA database to determine the correlation between CNV and DNA methylation and ESPL1 expression in LUAD." (PMID 35814478, 2022). "Numerous other genes such as ESPL1, DOCK8, ARID3A, PFKFB4, ANKZF1, BANP and GRB7 showed elevated expression rates, some of which are known or suspected to be involved in cancer development and/or progression." (PMID 37193047, 2022). "We analysed cancer genomic datasets from the UCSC Xena website and found that TTK, CDC25A, and ESPL1 were highly expressed in EC tissues compared with normal tissues." (PMID 33282948, 2020). "Clinical datasets and cancer genomic datasets from the cBioPortal website were analysed, and the results showed that in cases with TTK, CDC25A, and ESPL1 amplification, EC patients had worse survival outcomes." (PMID 33282948, 2020). "In various types of cancers, numerous studies have now documented a link between EIF4A3, SMC3, ESPL1, CDC25B, CCNA2, or AURKA and their response to therapy." (PMID 32454908, 2020). "TMPO-AS1 likely sequesters hsa-let-7b-5p, relieving repression of ESPL1 and E2F8, thus, upregulation of hsa-let-7b-5p could disrupt this ceRNA network, attenuating cancer progression by simultaneously targeting oncogenic transcripts and their sponge lncRNA." (PMID 41268575, 2025).
cancer (continued). "A previous cancer study discovered frequent alterations in STAG2 and ESPL1 in bladder cancer, which suggests that it may be involved in bladder tumorigenesis through sister chromatid cohesion and segregation process." (PMID 37006282, 2023). "Although prior research has revealed a link between ESPL1 and the development of cancer, no systematic pan-cancer analysis has been conducted." (PMID 37006282, 2023). "Considering that ESPL1 is still inadequately studied in cancer and there are no relevant pan-cancer analyses, the main aim of this study was to perform a systematic full-scale pan-cancer analysis of tumor samples from public databases." (PMID 37006282, 2023). "However, although researchers have gained some insight into the cell cycle regulation by ESPL1, more is needed to know whether and how it drives tumorigenesis, progression, and metastasis.There are no relevant pan-cancer analyses to date." (PMID 37006282, 2023). "Furthermore, despite the fact that ATF4 itself was not deregulated by Ocoxin in all the analyzed cancer models, it arises as a central protein in the correlation among the genes altered by the compound (except for KIF20A, RAD54L and ESPL1) in common in COAD, PAAD, PRAD and TNBC." (PMID 40176904, 2025). "However, most other cancers showed a negative correlation with CD4+ T cells, which may be one of the reasons why the high expression of ESPL1 in THYM exhibited a better prognosis." (PMID 37006282, 2023).
tumor (31 papers, 2011 to 2025). "Lastly, MKI67, UHRF1, and ESPL1 are associated with tumor proliferation and epigenetic regulation, with UHRF1 contributing to DNA methylation and DDR‐related transcriptional control." (PMID 40405535, 2025). "Genes such as BUB1, TPX2, and ESPL1 demonstrated significant associations with patient survival outcomes and tumor progression, suggesting their potential utility as prognostic biomarkers for risk stratification and treatment selection." (PMID 39596419, 2024). "Meanwhile, the overexpression of ESPL1 was significantly associated with higher tumour purity and lower immune cell levels in TME." (PMID 38813236, 2024). "Organoid lines also exhibited somatic mutations in RCC‐related genes which were in concordant with respective tumor including ESPL1, SMARCB1, RAB21, NCOR1, NLRC5, NOTCH2, and FOXA2 mutations." (PMID 38923304, 2024). "An interesting note is that a strong positive correlation exists between ESPL1 (gene that encodes Separase protein) and FoxM1 transcripts across various human tumor tissues, suggesting a relationship between FoxM1 and Separase expression in human cancer." (PMID 29780443, 2018). "Therefore, constitutive activation of ESPL1 can lead to aneuploidy, DNA damage, and the loss of crucial tumor suppressor gene sites, which are associated with tumor growth and disease progression." (PMID 41268575, 2025). "Hence, we utilised different algorithms to investigate the association between ESPL1 expression and the tumour microenvironment (TME) from multiple perspectives." (PMID 38813236, 2024). "Herein, we downloaded raw data from numerous publicly available databases and then applied R software and online tools to explore the association of ESPL1 expression with prognosis, survival, tumor microenvironment, tumor heterogeneity, and mutational profiles." (PMID 37006282, 2023). "Next, the association between ESPL1 expression and tumor immune infiltration was analyzed." (PMID 35814478, 2022). "Next, focusing specifically on BC, we used the UALCAN database to compare ESPL1 expression in tumor vs. normal breast tissues." (PMID 41268575, 2025). "We found that ESPL1 gene was significantly overexpressed in tumors, metastatic tissues, and circulating tumor cells, with tumor samples showing an overall 4-fold increase in expression compared to adjacent normal tissue of BC patients." (PMID 41268575, 2025). "Then, we analysed the relationship between ESPL1 mRNA expression and various clinical characteristics of BC patients, finding that ESPL1 expression was significantly correlated with patient age and tumour grade (p < 0.05)." (PMID 38813236, 2024). "This study also integrated, for the first time, the correlation between ESPL1 expression and the tumor microenvironment." (PMID 37006282, 2023). "Most tumor scores decreased with the increase in expression of ESPL1, but the opposite was true for THCA." (PMID 37006282, 2023). "Analysis of GDSC and CTRP databases identified drugs negatively correlated with ESPL1, suggesting that tumor cells with high ESPL1 expression are likely to be more sensitive to these drugs." (PMID 37006282, 2023). "Results showed that in LUAD, ESPL1 DNA methylation level was significantly lower in tumor tissues than in normal tissues." (PMID 35814478, 2022). "Two hub genes, CDCA5 and ESPL1, identified as probably playing tumor-promotive roles, have great potential to be utilized as novel therapeutic targets for EOC treatment." (PMID 34143800, 2021). "For example, a homozygous mutant of ESPL1 leads to a high level of aneuploidy thus acting as a tumor suppressor." (PMID 32547963, 2020).